TNF (tumor necrosis factor)
Diseases named in the same sentence as TNF in open-access papers (continued):
Sharing a sentence is not in itself a finding about the gene and the disease.
heart failure (continued). "Tnf receptors bind tumor necrosis factor alpha (Tnf-α), which has been demonstrated to have cardio-depressant properties in heart-failure or ischemic injury." (PMID 33114658, 2020). "TNF-alpha concentration increases in case of heart failure and is an independent predictor of mortality." (PMID 33203171, 2020). "Mice transgenic to IFN-γ developed a TNF-α-dependent inflammatory dilated cardiomyopathy with fibrosis and heart failure, and a very similar phenotype was developed by mice constitutively expressing active IKK2." (PMID 33351798, 2020). "Early studies identified TNF-α as a potential therapeutic target due to its known role as a pro-inflammatory mediator in heart failure." (PMID 33041853, 2020). "Then, the high selectivity of these MNPs to pre-concentrate two kind of Heart failure biomarkers: TNF-α (2–20 ng/mL) and IL-10 (10–100 ng/mL) in a complex medium (artificial saliva) after five hours of biofunctionalization process was studied." (PMID 32878151, 2020). "In the DEF group, the high circulating TNF-α level probably prevented bacterial proliferation, but triggered cardiac failure." (PMID 32365668, 2020). "The optimal use of diuretics, ACE inhibitors, beta-blockers, and standard treatment with digoxin for heart failure can significantly reduce circulating TNF levels." (PMID 33273955, 2020). "A prolonged NF-κB activation promotes heart failure by evoking signals that induce chronic inflammation through the enhancement of cytokines including tumor necrosis factor, IL-1, and IL-6, commencing to endoplasmic reticulum stress responses and cell death." (PMID 32775437, 2020). "The two water extracts of P. cubensis and hot-water extract of Pan cyanescens mushrooms also significantly reduced the ET-1-induced TNF-α, a pro-inflammatory cytokine involved in the progression of pathological hypertrophy and heart failure." (PMID 33339902, 2020). "Inflammatory cytokines such as TNF-α are overexpressed during heart failure and have been linked with increased MMP levels, contributing to ECM dysregulation and heart failure." (PMID 32363184, 2020). "Serum levels of tumor necrosis factor-alpha (TNF-α) are elevated in patients with heart failure (HF) and are an independent predictor of poor prognosis for the disease." (PMID 33270628, 2020). "The obtained results have proven that our MNPs can represent a promising tool for rapid pre-concentration of heart failure biomarkers (TNF-α/IL-10) in saliva." (PMID 32878151, 2020). "Increased adiponectin levels have been found in atrial and peripheral adipose tissue under the stimulation of eicosapentaenoic acid in a rabbit heart failure model, accompanied by reduced tumor necrosis factor and decreased incidence of AF." (PMID 33424438, 2020). "BEX1 induction during heart failure coincides with increased expression of proinflammatory genes such as tumor necrosis factor-α (TNFα)." (PMID 32164190, 2020). "Anti-TNF agents have been shown to increase death related to heart failure among patients with rheumatoid arthritis." (PMID 31025187, 2019). "In comparison with the control group, the concentrations of interleukin-1α, interleukin-6, interleukin-8, and tumor necrosis factor were significantly higher in the serum of dogs with dilated cardiomyopathy complicated by Class II-IV heart failure." (PMID 31749587, 2019). "Raised circulating levels of inflammatory cytokines, such as TNF-α, are also reported in patients suffering from heart failure (HF), with increasing levels according to disease severity." (PMID 30744018, 2019). "Taken together, our findings demonstrated that CGA effectively alleviated TNF‐α overexpression induced injury in a TAC heart failure mouse model and protected hiPSC‐CMs from TNF‐α–induced apoptosis." (PMID 31033175, 2019). "Statins had also been reported to decrease levels of C-reactive protein, interleukin-6, TNF-α, improve left ventricular function among individuals with heart failure." (PMID 31627722, 2019).
heart failure (continued). "In the current study, evidence from our in vivo study demonstrated that CGA has cardioprotective effects and mitigated TNF‐α–induced toxicity in a TAC heart failure mouse model." (PMID 31033175, 2019). "In the same manner, amiodarone, an antiarrhythmic drug that improves the long-term prognosis of heart failure, has been shown to inhibit the production of TNF-α and IL-6." (PMID 30935055, 2019). "The use of anti-TNF drugs for patients having severe heart failure (NYHA class III–IV) elevates mortality rate, rendering their use unsuitable." (PMID 31025187, 2019). "We firstly confirmed the cardioprotective effects of CGA in transverse aortic constriction (TAC)‐induced heart failure mouse model, through mitigating the TNF‐α–induced toxicity." (PMID 31033175, 2019). "The results of in vivo experiments show that CGA has cardioprotective effects and inhibited the high expression of TNF‐α in a heart failure mouse model." (PMID 31033175, 2019). "In particular, pimobendan has been shown to decrease the production of intracardiac IL-1β, IL-6, TNF-α and nitric oxide by inhibiting the activation of NFκB in mouse models of heart failure." (PMID 30935055, 2019). "Type D personality was shown to be associated with increased tumor necrosis factor-alpha (TNF-alpha) levels, which have been implicated in the pathogenesis of heart failure." (PMID 31002696, 2019). "Tumor necrosis factor-α (TNF-α) is a biomarker of inflammation that occurs in patients suffering from heart failure (HF)." (PMID 30744018, 2019). "Transgenic mice with a cardiac-specific TNF-α overexpression display heart failure, cardiac dilatation, fibrosis, altered contractile function, Ca2+ handling defects, and premature death." (PMID 31489895, 2019). "For instance, the levels of serum cytokines such as TNF-α, IL-6, and IL-1β are related to the severity of heart failure." (PMID 29511093, 2018). "Increased production of cytokines, especially inflammatory cytokines such as tumor necrosis factor alpha (TNFα), interleukin-1 (IL-1) or IL-6, is responsible, at least in part, for cardiac dysfunction in patients with heart failure." (PMID 27995459, 2018). "There is considerable evidence that inflammatory cytokines such as IL-6, IL-1 and TNF-α are upregulated in plasma of heart failure patients, as well as in the failing myocardium itself." (PMID 29674727, 2018). "The locally produced autocrine TNF-α was found to have a noticeable role in alcohol-related heart failure." (PMID 29487525, 2018). "Pro-inflammatory cytokines including TNF, IL-1β, and IL-6 are upregulated with decreased heart function, and are activated earlier in heart failure than the classic neurohormones." (PMID 29900007, 2018). "Several studies have shown raised levels of inflammatory cytokines, such as tumor necrosis factor (TNF), interleukins from the IL-1 and IL-6 families in plasma, and circulating leukocytes in heart failure patients." (PMID 29900007, 2018). "Consistent with findings from animal studies implicating TNF-α in the pathogenesis of heart failure, circulating levels of TNF-α have consistently been shown to be elevated in patients with chronic heart failure." (PMID 29875701, 2018). "The levels of inflammatory cytokines (tumour necrosis factor-α [TNF-α], interleukin (IL)-1β, and IL-6) are increased in patients with heart failure." (PMID 29511093, 2018). "As a result the anti-TNF treatment is contraindicated in all patients with heart failure and a substantial portion of patients with RA and impaired heart function are not able to benefit from the treatment." (PMID 29895751, 2018). "IS also upregulated mRNA expression of key cytokines playing role in heart failure progression: IL-1β, IL-6 and TNF-α, in cultured monocytic cells, indicating a pro-inflammatory effect of IS." (PMID 30200452, 2018). "Attempts to integrate TNF-α antagonist into the realms of therapeutic medicine has been suggested, with possible effectiveness for symptomatic heart failure patients." (PMID 29487525, 2018).
heart failure (continued). "In patients with advanced heart failure, myocardial expression of TNF-α was abundantly increased, probably contributing to maladaptive mechanisms implicated in the development of cardiac hypertrophy and dysfunction." (PMID 30177883, 2018). "Unlike during physiological conditions, where TNFα levels are low, during heart failure both myocardial macrophages and cardiomyocytes produce a plethora of TNFα; during congestive heart failure, for example, TNF-α were found to be elevated in advanced stages." (PMID 29487525, 2018). "Since TNF-α was found to have a noticeable role in alcohol-related heart failure, we are interested in the role of cytokines in particular TNF-α in development and progression of heart failure." (PMID 29487525, 2018). "For example, during MI, myocarditis, or heart failure, both tumor necrosis factor α (TNF-α) and interleukin 6 (IL-6) levels increase in proportion to the severity and duration of congestive heart failure (CHF)." (PMID 30104479, 2018). "One multicenter clinical trial of 1,200 patients with progressed heart failure shows that the up-regulated circulating levels of TNF, IL-6 and the soluble TNF receptors sTNFR1 and sTNFR2 are related with increased mortality." (PMID 28978156, 2017). "Serum concentrations of TNF-α, IL-1β and IL-6 were increased along with the severity of heart failure and the decrease of SNAQ scores as well." (PMID 29155861, 2017). "ATTACH trial evaluated a TNF-α antibody infliximab in 150 patients with moderate-to-severe heart failure." (PMID 28460644, 2017). "High levels of proinflammatory cytokines, including TNF-α, IL-6, IL-1β, and IL-2, have a profound effect on pathogenesis and prognosis in heart failure." (PMID 29201273, 2017). "Studies in heart failure patients demonstrate that high levels of TNF-α are expressed within failing human myocardium, suggesting its role in the progression of heart failure." (PMID 28460644, 2017). "It has been delineated that the gene polymorphisms of proinflammatory cytokines such as interleukin- (IL-) 6 and tumor necrosis factor-α (TNF-α) are associated with the susceptibility and prognosis of DCM or heart failure." (PMID 28572699, 2017). "In the myocardium, TNFα contributes to reversible and irreversible ischemia/reperfusion injury, post myocardial infarction remodeling, and heart failure development." (PMID 27803674, 2016). "For example, in a model of heart failure induced by transgenic expression of the cytokine tumor factor alpha (TNFα), the recognition of the ligand ATP for KATP channels was significantly impaired." (PMID 26949448, 2016). "After finding increased levels of TNF in patients with heart failure, trials were conducted using TNFi as treatment for heart failure; none demonstrated benefit and one reported worse outcomes in patients treated with TNFi." (PMID 27906042, 2016). "TNF-alpha had the downregulation effect on eNOS expression in heart failure patients and obese mice." (PMID 27936072, 2016). "Tenth, obese patients with heart failure produce lower concentrations of tumor necrosis factor-α, which can further be lowered by the production of soluble receptors that bind this factor by subcutaneous adipose tissue." (PMID 27906989, 2016). "IL-6 and TNFα have been demonstrated to increase with the severity of heart failure and predict mortality." (PMID 26070197, 2015). "Cardiac‐specific expression of TNF‐α can result in increased apoptosis and ventricular dilatation, ultimately leading to heart failure and death." (PMID 26471858, 2015). "In cell culture, myogenin expression is suppressed in differentiating myocytes treated with tumor necrosis factor-α (TNF-α), a cytokine that commonly increases during heart failure." (PMID 26452256, 2015). "TNF-α and IL-6 circulating levels are elevated and correlate with disease severity in heart failure." (PMID 26539513, 2015).
heart failure (continued). "A clinical trial for semapimod, an anti-inflammatory agent which inhibits p38 activity, was started for heart failure patients, but was apparently terminated upon the disclosure of the discouraging results of the TNF-α-targeted clinical trials." (PMID 26029107, 2015). "Other biomarkers that established a link between heart failure and inflammation include tumor necrosis factor-alpha, and the pro-inflammatory (e.g. interleukin–6) and anti-inflammatory (interleukin–10) cytokines." (PMID 26506526, 2015). "Taken together, serum NAMPT, by regulating the expression of different cytokines such as TNFα and IL-6, takes part in the heart failure progression in DCM patients." (PMID 26389889, 2015). "The recent experience with interventions targeting the Tumor Necrosis Factor (TNF)-a system in patients with heart failure highlighted the unpredictable consequences of interfering with cytokine signaling." (PMID 26273700, 2015). "The study indicated serum NAMPT suppresses directly or indirectly the expression of important cytokines (IL-6 and TNFα) involved in heart failure progression in DCM patients." (PMID 26389889, 2015). "TNF-α-mediated inflammation is balanced by secretion of the anti-inflammatory cytokine IL-10, and low IL-10/TNF-α are associated with pathophysiology of heart failure." (PMID 25954207, 2015). "Recent data, supporting our findings, have described an inverse relationship between HRV indices and TNF-alpha levels in heart failure but also in healthy subjects under stressful situations." (PMID 25207649, 2014). "Chronic chagasic cardiomyopathy, the main manifestation of CD, occurs in a TNF-enriched milieu and frequently progresses to heart failure." (PMID 25140115, 2014). "This explains why clinical trials with anti-TNF therapies were disappointing although overexpression of TNF, which is positively correlated with heart failure in patients, leads to experimental heart failure." (PMID 24611063, 2014). "It is well established that the TNF-alpha system is involved in the pathophysiology and progression of heart failure." (PMID 24770373, 2014). "Tumor necrosis factor-α (TNF-α), a critical factor causing heart failure and when overexpressed prolonging APD and promoting ventricular arrhythmias, suppresses HERG function." (PMID 24475014, 2014). "Furthermore, NAC may inhibit NF-κB-mediated expression of pro-inflammatory cytokines and apoptosis-associated genes as was observed in an in vivo study of heart failure, in which the inhibition of TNF-α-related signal transduction by NAC promoted the recovery of myocardial structure and function." (PMID 24889421, 2014). "It has been suggested that the predominant mechanism of upregulation of TNF-α production is secondary to advanced heart failure itself, such as low cardiac output and intestinal bacterial translocation." (PMID 25303100, 2014). "The assumption that our set-up is a model for moderate heart failure is supported by the fact that TNF-α levels remained stable in TAC mice." (PMID 24523936, 2014). "In several clinical trials, pentoxifylline therapy was reported to reduce circulating levels of C-reactive protein, FASL, and TNF-α in heart failure patients." (PMID 23740214, 2013). "For example, TNF overexpression leads to heart failure and its endogenous expression is positively correlated with heart failure." (PMID 23325387, 2013). "In both groups, a considerable improvement of ventricular function and clinical symptoms of cardiac insufficiency was achieved, as well as a decrease in the concentration of IL-6 and TNF-alpha." (PMID 23566246, 2013). "First, cardiac function was improved, in qualitative agreement with data obtained in healthy and transgenic (over-expression of tumor necrosis factor α, which induces heart failure) rodent models." (PMID 24124584, 2013). "The authors concluded that over-expression of TNF-α and subsequent loss of β-adrenergic responsiveness contributes to the decrease in HRV, observed in heart failure." (PMID 23847549, 2013).
heart failure (continued). "The expression of TNF-α was significantly lower in MI-induced heart failure treated with TLR4-SiRNA than in that treated with hGAPDH-SiRNA for 2 weeks." (PMID 23874864, 2013). "On the other side, infusion of TNF-α or intracardiac overexpression of TNF-α in animals leads to heart failure." (PMID 24489446, 2013). "The clinical relevance of these findings has not yet been tested by a clinical trial testing neutralization of TNF-α in patients with acute/decompensated heart failure." (PMID 23740214, 2013). "On one side, TNF-α is a valuable biomarker, for its correlation with enhanced brain natriuretic peptide and adverse clinical outcome in patients with heart failure." (PMID 23530831, 2013). "The expressions of IL-1β, TNF-α, and IL-6 were significantly higher in MI-induced heart failure treated with hGAPDH-SiRNA than in sham." (PMID 23874864, 2013). "Plasma TNF-α levels are significantly increased in patients with cardiovascular disease, particularly myocardial infarction (MI) and heart failure." (PMID 23704873, 2013). "Angiotensin II, Tumor Necrosis Factor alpha (TNF-α) and norepinephrine are neurohormones implicated in the development of cardiac hypertrophy and progression to end-stage human heart failure." (PMID 24265619, 2013). "Such disparity illustrates our incomplete understanding of TNFα within heart failure pathophysiology." (PMID 23704873, 2013). "TNF-α and IL-6 have both been repeatedly reported to correlate with cardiac contraction and relaxation deficits after burn trauma but also in heart failure patients." (PMID 23663695, 2013). "In fact, elevated circulating levels of TNF-α and IL-6 have been reported as independent predictors of mortality in patients with heart failure." (PMID 22569420, 2012). "TNF-α-positive cells were observed in 10 of the 11 cases with heart failure, with a median of 4 immunostained cells (range: 0 to 22 cells/mm2), and in 4 of the 10 cases without heart failure." (PMID 22811738, 2012). "Severe heart involvement leading to heart failure seems to be multifactorial and associated with the presence of IFN-γ- and TNF-α-producing cells." (PMID 22811738, 2012). "Further, TNF blockade in dogs with heart failure leads to a restoration of mitochondrial respiratory function in the left ventricle." (PMID 23056347, 2012). "Previous studies have demonstrated that cardiac-specific expression of TNF-α result in myocardial inflammation, cardiac hypertrophy, progressive dilatation and increased apoptosis, which leads to heart failure and death." (PMID 21235788, 2011). "The progression of heart failure usually entails a local rise in pro-inflammatory cytokines, such as TNF-α, which mainly act in an autocrine fashion." (PMID 21625432, 2011). "Reduction of TNF-alpha activity using soluble receptors has demonstrated beneficial effects in animal models of heart failure." (PMID 20398245, 2010). "In conclusion, our study offers a new mechanism of increased serum TNFα concentrations in heart failure." (PMID 20224758, 2009). "Increased expression of c-fos was viewed as an adaptive response for maintaining cardiac output after stimulation of with TNF or AngII, as in isolated adult cardiac myocytes or heart failure, ischemic injury and stress-induced hypertrophy models." (PMID 19210763, 2009). "As a third possibility our data suggest at least in theory a new mechanism for TNFα production of PBMC in heart failure." (PMID 20224758, 2009). "For example, TNF-α was proved to modulate heart failure by provoking hypertrophic growth in cardiac myocytes, and a recent study in neonatal cardiac myocytes showed that TNF was sufficient to trigger cardiac myocyte hypertrophy." (PMID 19210763, 2009). "For instance, TNF-α inhibitors such as etanercept and infliximab, initially developed for autoimmune diseases, have demonstrated potential in reducing systemic inflammation and improving cardiac function in certain subsets of heart failure patients." (PMID 40787514, 2025).